RNF187 (ring finger protein 187)
Description:
E3 ubiquitin-protein ligase that acts as a coactivator of JUN-mediated gene activation in response to growth factor signaling via the MAP3K1 pathway, independently from MAPK8.
Synonyms: RACO-1; RACO1
Tractability: PROTAC: UniProt records ubiquitination sites on it; ubiquitination databases record sites on it.
Gene: Protein-coding gene on chromosome 1 (228,487,382 to 228,499,899, forward strand). Ensembl gene ENSG00000168159.
Subcellular location: Cytoplasm; Nucleus
Subcellular location (Human Protein Atlas): Cytosol; Nucleoplasm
Gene Ontology:
Molecular function: protein binding; ubiquitin-protein transferase activity; ubiquitin protein ligase activity
Biological process: positive regulation of DNA-templated transcription; proteasome-mediated ubiquitin-dependent protein catabolic process; protein autoubiquitination; protein K48-linked ubiquitination; positive regulation of cell population proliferation; protein ubiquitination
Cellular component: cytoplasm; cytosol; nucleoplasm; nucleus
Genetic constraint (gnomAD): Loss-of-function variants: 18 observed, 14.79 expected, observed/expected ratio (o/e) 1.22, 90% interval 0.84 to 1.76. The synonymous counts are far from expectation, so gnomAD's model fits this gene poorly and the ratio says little. Missense variants: 328 observed, 243.28 expected, observed/expected ratio (o/e) 1.35, 90% interval 1.23 to 1.48. Synonymous variants: 164 observed, 115.46 expected, observed/expected ratio (o/e) 1.42, 90% interval 1.25 to 1.62.
Homologues: Orthologues: chimpanzee RNF187 (99% identical), macaque RNF187 (99% identical), pig RNF187 (94% identical), guinea pig RNF187 (89% identical).
Diseases named in the same sentence as RNF187 in open-access papers:
RNF187 is named in the same sentence as 13 diseases in open-access papers, as found by Europe PMC text mining. Sharing a sentence is not in itself a finding about the gene and the disease. The quoted sentences say what the papers report.
hepatocellular carcinoma (8 papers, 2017 to 2025). A malignant tumor that arises from hepatocytes. "It has been reported that abnormal activation of Notch signal is related to the metastasis of hepatocellular carcinoma, and NOTCH1 can activate RNF187 promoter to promote the invasion and metastasis of hepatocellular carcinoma." (PMID 32963562, 2020). "Our results revealed that elevated expression of RNF187 induced hepatocellular carcinoma cell epithelial to mesenchymal transitions, and represented a novel marker for predicting the poor prognosis of HCC." (PMID 29254210, 2017). "For instance, Fbxw7 regulates YAP protein stability by targeting YAP for ubiquitination and proteasomal degradation in hepatocellular carcinoma; SHARPIN and RNF187 promote YAP degradation via inducing YAP K48-dependent poly-ubiquitination." (PMID 37349820, 2023). "However, the expression and function of RNF187 in hepatocellular carcinomas (HCC) remains unclear." (PMID 29254210, 2017).
breast carcinoma (4 papers, 2020 to 2025). "Pharmacologic inhibitors such as verteporfin, which disrupt the YAP–TEAD interaction, have shown efficacy across multiple breast cancer subtypes, while upstream modulators like RNF187 have been proposed as potential targets in triple-negative disease." (PMID 40731926, 2025). "Our research focused on RNF187 function in human breast cancer, and we discovered that RNF187 functions as an inhibitor of the Hippo/YAP axis, which subsequently inhibits cancer progression in triple-negative breast cancers." (PMID 35165289, 2022). "Since our previous study showed that RNF187 played tumor suppressor roles in triple-negative breast cancer, we further investigated its role in luminal-type breast cancer." (PMID 35165289, 2022). "RNF187 facilitated breast cancer cell growth and apoptosis resistance in both cell culture and xenograft mouse models." (PMID 35165289, 2022). "The beta-Gal assay showed that RNF187 depletion could significantly enhance breast cancer cell senescence." (PMID 35165289, 2022). "RNF187 depletion inhibited breast cancer growth and facilitated cell death." (PMID 35165289, 2022).
breast carcinoma (continued). "Interestingly, RNF187 has poor prognosis in all breast cancer patients." (PMID 32198343, 2020). "However, RNF187 shows different prognostic trends in different subtype of breast cancer." (PMID 32198343, 2020). "Similarly, in breast cancer cells, the E3 ligase RNF187 leads to ubiquitination of YAP, and RNF187 levels correlate inversely with YAP protein levels." (PMID 37031213, 2023).
non-small cell lung carcinoma (4 papers, 2019 to 2025). A group of at least three distinct histological types of lung cancer, including non-small cell squamous cell carcinoma, adenocarcinoma, and large cell carcinoma. "In non-small cell lung cancer (NSCLC), RNF187 promotes EMT and apoptosis resistance by activating MAPK/PI3K signaling pathways." (PMID 41208892, 2025). "Overexpression of RNF187 was shown to induce EMT and resistance to apoptosis in non-small-cell lung cancer cells through activation of MAPK and PI3K signaling." (PMID 31477177, 2019).
triple-negative breast carcinoma (3 papers, 2020 to 2025). An invasive breast carcinoma which is negative for expression of estrogen receptor (ER), progesterone receptor (PR), and human epidermal growth factor receptor 2 (HER2). "The E3 ligase RNF187 facilitates YAP ubiquitination in triple-negative breast cancer cells, where decreased RNF187 expression is linked to increased YAP protein levels." (PMID 40478800, 2025). "Our previous study showed that RNF187 functioned as a negative regulator in triple-negative breast cancer by modulating Hippo signaling." (PMID 35165289, 2022). "In ER alpha positive type, RNF187 relates to poor prognosis, while RNF187 shows the trend to be a good prognostic marker (P = 0.32) in triple negative breast cancer." (PMID 32198343, 2020). "In order to investigate the role of RNF187 in triple negative breast cancer cells, we utilized BT549 and MDAMB231 cells to carry out most of the experiments." (PMID 32198343, 2020).
osteosarcoma (2 papers, 2020 to 2022). A usually aggressive malignant bone-forming mesenchymal neoplasm, predominantly affecting adolescents and young adults. "The 2- and 5-year RFS in the RNF187low group were apparently higher than those in the RNF187high group, indicating that RNF187 expression predicts an unfavorable prognosis for patients with osteosarcoma." (PMID 32047542, 2020). "However, the roles of RNF187 in osteosarcoma (OS) are unclear." (PMID 32047542, 2020).
liver cancer (1 paper, 2019). An epithelial or non-epithelial malignant neoplasm that arises from the liver. "In summary, our study clarified a key role of Notch1 and RNF187 in liver cancer metastasis." (PMID 31477177, 2019).
liver cirrhosis (1 paper, 2017). "However, other clinical characteristics including age, sex, HBsAg background, tumor differentiation, liver cirrhosis, preoperative serum alpha-fetoprotein (AFP), and Child-Pugh scores were not significantly related to the expression of RNF187." (PMID 29254210, 2017).
tumor (10 papers, 2017 to 2025). "Clinically, our data displayed that the RNF187 overexpression in OS samples associated with shorten overall survival (p=0.001) and high tumor recurrence (p=0.001) in postoperative OS patients." (PMID 32047542, 2020). "Both the high expression of Notch1 and RNF187 were associated with aggressive tumor behavior." (PMID 31477177, 2019). "Positive RNF187 staining was located in the cytoplasm of tumor cells and showed substantial heterogeneity in the different tumor specimens." (PMID 32047542, 2020). "IHC analysis of liver orthotopic xenograft tumor of nude mice revealed that RNF187, Vimentin, and Snail expression levels were higher in tumors derived from HCCLM6-shcontrol cells than in tumors derived from HCCLM6-shNotch1." (PMID 31477177, 2019). "In view of the acknowledged proto-oncoprotein of JunD, it is not unreasonable to draw the conclusion that a high level of RNF187 is a promoter of tumor progression." (PMID 29254210, 2017). "Collectively, these data indicated Circ_0000915 and RNF187 may play oncogenic roles and promote propranolol resistance in IHs, while miR-890 may act as a tumor suppressor and inhibit propranolol resistance in IHs." (PMID 36167680, 2022). "Our data showed that RNF187 depletion reduced the tumor growth rate in vivo." (PMID 35165289, 2022). "Firstly, the expression of RNF187 is higher in OS tissues and cells than that in matched nontumorous tissues and the fetal osteoblastic cell, and low level of RNF187 decreased accordingly the capacity for tumor metastasis and invasion both in vitro and in vivo." (PMID 32047542, 2020). "This could be the first study showing the tumor suppressive function of RNF187 in cancer progression." (PMID 32198343, 2020). "Third, data from HCC patients demonstrated that overexpression of the RNF187 protein was significantly correlated with malignant phenotypes including larger tumor sizes, multiple tumors, and microvascular invasion, which are well established poor prognostic parameters.." (PMID 29254210, 2017). "However, in our current study, RNF187 functions as a tumor suppressor in TNBC progression." (PMID 32198343, 2020). "Immunohistochemical results revealed that RNF187 was located in the cell cytoplasm and nuclei of neoplastic cells and highly expressed in 94 cases with variable intensities (44.98%), while low level of RNF187 were found in 55.02% (low expression,115/209) tumor tissues." (PMID 29254210, 2017). "In this study, we observed that high expression levels of RNF187 was correlated with aggressive clinicopathologic features in HCC patients, including larger tumor size, tumor differentiation and TNM stage." (PMID 31477177, 2019). "Our previous studies showed that SHARPIN and RNF187 could promote YAP degradation and inhibit tumor progression." (PMID 36581998, 2022). "However, additional clinical features, containing age, sex, and site of primary tumor, were not significantly relevant to the RNF187 expression." (PMID 32047542, 2020). "In addition, we found that the forced expression of RNF187 in HCC cells could upregulate the level of c-Myc, which has been reported to be a powerful inducer of tumor cell EMT." (PMID 29254210, 2017). "Moreover, the high levels of RNF187 were frequently found in tissues of malignant phenotypes, such as microvascular/bile duct invasion, high TNM stage, multiple tumors, and large tumor sizes, which indicates a high level of RNF187 functions as a promoter of HCC." (PMID 29254210, 2017).
cancer (8 papers, 2019 to 2025). A tumor composed of atypical neoplastic, often pleomorphic cells that invade other tissues. "Since we showed that RNF187 is an important factor in maintaining cell growth and survival in luminal-type cancers, we further investigated the function of RNF187 via an unbiased approach." (PMID 35165289, 2022). "In previous studies, we characterized several E3 ubiquitin ligases involved in modulating Hippo signaling effectors and cancer progression, such as RNF187 and ZNF213." (PMID 35820928, 2022). "RNF187, a E3 ubiquitin ligase to enable ubiquitin-protein transferase activity, has been widely reported to be an oncogene in multiple cancer types." (PMID 36167680, 2022). "Gene ontology-biological process analysis showed that RNF187 depletion affects several aspects of cancer biological processes, including apoptosis, cell cycle arrest, and the DNA damage response." (PMID 35165289, 2022). "The interesting findings increase the proteolytic regulation of Hippo/YAP signaling, but also reveal the “multi-face” role of RNF187 in different cancer type backgrounds." (PMID 32198343, 2020). "The rescue experiment in trans-well assay was carried out with consistent results: RNF187 depletion significantly promotes cancer cell invasion, which effect is rescued by further YAP knocking down." (PMID 32198343, 2020). "RNF187 depletion promotes cancer cell progression and activates Hippo signaling in multiple TNBC cell lines." (PMID 32198343, 2020). "However, we found an opposite cancer phenotype in luminal-type cancer models, in which RNF187 was required for cell growth and apoptosis resistance." (PMID 35165289, 2022). "Although several studies showed that RNF187 could potentially been an oncogene, our understanding is that RNF187 function is cancer type dependent." (PMID 32198343, 2020). "Increased expression of RNF187 has been correlated with poor survival in many cancers." (PMID 31477177, 2019). "RING finger protein 187 (RNF187) was recently revealed to be a driver of several cancers, but its expression pattern and biological function in HCC are unknown." (PMID 31477177, 2019). "Notch1-driven HCC progression could be reversed by depletion of RNF187, whereas overexpression of RNF187 counteracted the inhibition of cancer progression mediated by Notch1 knockdown." (PMID 31477177, 2019). "Moreover, overexpression of RNF187 counteracted the inhibitory effect of Notch1 knockdown on cancer progression." (PMID 31477177, 2019). "The E3 ubiquitin ligase RNF187 has been reported to regulate RAS-AP1 signaling and facilitate cancer progression." (PMID 35165289, 2022). "Having shown that RNF187 can inhibit Hippo/YAP signaling and cell migration and invasion capacity, we experimented further to provide the logic link between cancer cell phenotype and Hippo signaling." (PMID 32198343, 2020).
infection (2 papers, 2017 to 2022). The state of being infected such as from the introduction of a foreign agent such as serum, vaccine, antigenic substance or organism. "Validation of the gene expression levels obtained by RNA-seq specific to the HCV group (BIRC5 and SLC22A1), the HBV group (CLEC1B), and the group without infection (FGFR4, HSF1, RNF187, HSP90AB1, and HSPB1) was performed using the real-time PCR technique." (PMID 36557005, 2022).
RNF187 also shares sentences with these, for which no sentence is quoted: breast tumors (1 paper); colon epithelial tumor (1); hemangioma (1).